MSLN (mesothelin)
Diseases named in the same sentence as MSLN in open-access papers (continued):
Sharing a sentence is not in itself a finding about the gene and the disease.
ovarian carcinoma (continued). "Physiologically, mesothelin (MSLN) exhibits low expression in mesothelial tissues, such as pleura, peritoneum and pericardium, but high expression in various cancers, including mesothelioma, pancreatic, lung, ovarian cancers, acute myeloid leukemia and triple negative breast cancers." (PMID 38067344, 2023). "In addition, 15 patients with MPM, PDAC, or ovarian cancer were given lentiviral-transduced anti-mesothelin (murine SS1 scFv) CD3ζ/4-1BB CAR T-cells with or without cyclophosphamide." (PMID 37020537, 2023). "Preliminary clinical trials using the novel anti-MSLN CAR-T cell therapy in autologous T cells from three patients with chemotherapy-refractory metastatic ovarian cancer showed promising results, indicating its potential as an immunotherapeutic approach for advanced ovarian cancer." (PMID 37766309, 2023). "However, the related molecular mechanisms of MSLN in chemoresistance in ovarian cancer have not been elucidated." (PMID 35692779, 2022). "Studies on ovarian cancer have found that the specific binding of MSLN and carbohydrate antigen 125 (CA125) can mediate and enhance the adhesion of tumor cells, which promotes the extensive implantation and metastasis of ovarian cancer in the pelvic and abdominal cavity." (PMID 35692779, 2022). "Mesothelin is a promising target for CAR T cell therapy, because up to 30% of cancers are detected with high levels of mesothelin expression, such as epithelial mesothelioma, pancreatic cancer, ovarian cancer, squamous cell carcinomas, adenocarcinomas and triple negative breast cancer." (PMID 33777013, 2021). "The role of MSLN in anoikis resistance that we observed is not restricted to ovarian cancer cells." (PMID 32612258, 2020). "However, the relevance of MSLN expression in the peritoneal dissemination of ovarian cancer cells has not yet been addressed." (PMID 32612258, 2020). "Mesothelin is one such cell-surface glycoprotein that is expressed at low levels on normal mesothelial cells of the pleura, pericardium, peritoneum, and tunica vaginalis, whereas it is overexpressed in the majority of MPM, lung, pancreatic, and ovarian carcinomas." (PMID 28862644, 2017). "Furthermore, published evidence has shown that antigen-specific spontaneous immune response are beneficial for different solid malignancies—MSLN in pancreatic cancer, CA125 in ovarian cancer, and WT1 in mesothelioma —and has driven us to explore the expression of these antigens on MPM." (PMID 29100432, 2017). "Several mesothelin-based biological therapies i.e. chimeric antigen receptor (CAR T cells), monoclonal antibodies, antibody-drug conjugates are currently under clinical assessment in patients with advanced solid tumours, such as mesothelioma, lung, pancreatic and ovarian cancer." (PMID 29113296, 2017). "And finally, another important aspect regarding the mesothelin/MUC16 interaction is its potential contribution to homotypic (tumor cell-tumor cell) and heterotypic (tumor cell-mesothelial cell) cell interactions, especially important for the peritoneal spread in ovarian cancer patients." (PMID 27120790, 2016). "The aim of this study was to investigate whether other ovarian cancer-related biomarkers, Human Epididymis 4 (HE4), glycodelin, mesothelin, matrix metalloproteinase 7 (MMP7), and cytokeratin 19 fragment (CYFRA 21-1), could improve the performance of CA125 in detecting ovarian cancer earlier." (PMID 26819954, 2015). "Mesothelin could potentially be used as an alternative to [18F]FDG to avoid uptake in the gastrointestinal tract, but small peritoneal and pleural metastases that frequently occur in ovarian cancer in particular may be missed, substantially reducing the usability of mesothelin." (PMID 40923371, 2025).
ovarian carcinoma (continued). "The MSLN-directed antibody–drug conjugate, anetumab ravtansine, which consists of a human anti-MSLN antibody conjugated to the maytansinoid tubulin inhibitor, DM4, via a disulfide-containing linker, was found to be active against malignant mesothelioma and ovarian cancer with high MSLN expression." (PMID 36434635, 2022). "Mesothelin (MSLN) is a surface glycoprotein with low expression on normal cells and increased expression in many solid tumors including ovarian cancer." (PMID 38954005, 2024). "MSLN-targeted CAR T-cell therapy in PDX mouse models has been shown to be effective in mesothelioma, but efficacy has not been reported in ovarian cancer." (PMID 36166071, 2023). "There is currently no relevant report on the interaction between MUC4 and MSLN, but the interaction between MUC16 and MSLN plays an important role in the development of ovarian cancer." (PMID 37546424, 2023). "While CA125, HE4 and mesothelin are not specific for ovarian cancer, as they are known to be expressed in the normal müllerian tract, we did not detect peptides from either HE4 or mesothelin in the “Normal Pap test Core Proteome”." (PMID 33413078, 2021). "DKK1 protein expression did not change (p > 0.05) in two ovarian cancer cell lines stimulated with CA125 and anti-MSLN compared to the unstimulated cell line." (PMID 33613114, 2021). "This work also supports previous studies showing the potential of HE4, whilst suggesting that mesothelin, MMP7, and CYFRA 21-1 are not useful markers for the early detection of ovarian cancer." (PMID 26819954, 2015). "Surprisingly, CA125 and MSLN were not highly correlated even though CA125 has been described to be the ligand for MSLN and to be involved in the metastatic process in ovarian cancer." (PMID 23590973, 2013). "Notably, MSLN and CD19-CAR NK cells exhibited a negligible impact on SK-HEP-1 MSLN-negative cells, while decisively eliminating OVCAR-3 and SK-OV-3 MSLN-positive ovarian cancer cells in vitro studies." (PMID 40227616, 2025). "Conversely, known ovarian cancer targets MUC16 and MSLN were not epithelial-restricted and were expressed in both the fibroblast population (12.4% MUC16+, 53.1% MSLN+) and the malignant epithelial cell population (51.3% MUC16+, 78.5% MSLN+)." (PMID 34290299, 2021). "However, Zhao and coworkers reported that systemic infusion of CAR T cells that were constructed based on the N-terminus of mesothelin did not eliminate tumor cells in mice while, in contrast, our MSLN-CAR T cells were effective at shrinking ovarian cancer cell tumors in NCG mice." (PMID 38637885, 2024).
mesothelioma (249 papers, 2006 to 2026). A usually malignant and aggressive neoplasm of the mesothelium which is often associated with exposure to asbestos. "Serum mesothelin levels assisted in differentiating 217 patients with stage I or II epithelioid and biphasic mesothelioma from 1612 high-risk controls with a sensitivity of 32%." (PMID 41375064, 2025). "In this context, most receptor designs have targeted the tumor-associated antigen (TAA) mesothelin (MSLN), which is considered an attractive candidate given its limited expression in normal mesothelial cells and marked overexpression in mesothelioma." (PMID 41097726, 2025). "The SS1P immunotoxin, which consists of PE38 linked to an anti-mesothelin antibody, has shown effectiveness in treating mesothelioma and other tumors, which overexpress mesothelin in preclinical as well as clinical trials." (PMID 40519767, 2025). "For instance, in mesothelioma, a high MSLN expression was associated with an immunostimulatory TME characterized by increased infiltration of CD8+ T cells and CD68+ macrophages." (PMID 41335396, 2025). "We aimed to detect and characterize mesothelin gene expression in dogs and assess its diagnostic usefulness in canine mesotheliomas." (PMID 39315086, 2024). "In an orthotopic murine mesothelioma model expressing human mesothelin, treatment with a mesothelin-targeted Fab linked to a toxin eradicated tumors and induced TLS formation." (PMID 38361928, 2024). "We aimed to explore and characterize mesothelin gene expression in dogs and assess its use as a diagnostic biomarker for canine mesotheliomas." (PMID 39315086, 2024). "Mesothelin overexpression was observed in mesothelioma effusions, suggesting the effusion samples’ diagnostic usefulness for analyzing mesothelin expression in canine mesothelioma." (PMID 39315086, 2024). "In the present study, we evaluated a clinical mesothelioma cohort to study the association between MSLN and remodeling of the immune matrix of the tumor microenvironment (TME)." (PMID 37901248, 2023). "The unfortunate implication is that mesothelioma patients with a risk of poor prognosis are less likely to be suitable for anti‐MSLN targeted therapies." (PMID 37040900, 2023). "Loss of MSLN mRNA expression was also identified in a poor prognostic subgroup of mesothelioma in an integrative, multiplatform genome analysis of The Cancer Genome Atlas specimens." (PMID 37040900, 2023). "Serum mesothelin is a protein produced by mesothelium in response to acute and chronic states of inflammation and associated with mesothelioma development." (PMID 35987988, 2022). "Mesothelin (MSLN) is a glycophosphatidylinositol-linked cell surface protein highly expressed in several types of malignant tumors, including mesothelioma." (PMID 36380343, 2022). "HAND2 expression coincided with differential expression of the previously mesothelium- and mesothelioma-associated genes MSLN and WT1, as well as with GATA5 and MEIS2." (PMID 35354817, 2022). "Several new agents designed to target relapsed mesothelioma have also been developed, included mesothelin-targeted therapies and arginine deprivation for the treatment of arginosuccinate synthetase 1-deficient mesothelioma." (PMID 35008346, 2021). "Mesothelin is a cell-surface antigen implicated in tumor invasion, which is highly expressed in mesothelioma, lung, pancreas, breast, ovarian, and other cancers." (PMID 32993581, 2020). "High tissue expression of mesothelin has been linked to aggressive tumor behavior and worse prognosis in ovarian and pancreatic cancers as well as in mesothelioma." (PMID 31035965, 2019). "Mesothelin is the most studied serum biomarker for mesothelioma with the majority of literature assessing its diagnostic potential." (PMID 29454314, 2018).
mesothelioma (continued). "A meta-analysis study dealing with respective patient data searched a possible merit of serum mesothelin in the diagnosis, which included more than 200 patients with stages I and II mesothelioma and 1600 symptomatic or high-risk controls." (PMID 28335760, 2017). "Mesothelin is a glycosyl–phosphatidyl inositol-linked cell surface glycoprotein, which is highly expressed in mesothelioma, and lung, pancreas, breast, ovarian, and other cancers, and has been used as a tumor antigen of CAR T cells in several trials." (PMID 28288656, 2017). "This is the first investigation associated with usage of MSLN as a target molecule for mesothelioma treatments using doxorubicin-loaded EDV nanocells." (PMID 29059207, 2017). "We subsequently revealed that ERC is a homolog of the human mesothelin gene, which is the causative gene for mesothelioma 16,17." (PMID 25045139, 2014). "Consistent with previous studies, we found that pleural effusion and serum mesothelin has diagnostic utility for mesothelioma." (PMID 23009708, 2012). "Prior studies have associated high sMSLN levels with higher risk mesothelioma, but these recent results suggest that high sMSLN levels may impair the efficacy of anti-MSLN ADCs10." (PMID 40240561, 2025). "This preliminary study suggests that mesothelin could serve as a vital diagnostic biomarker of canine mesotheliomas for tissue- and effusion-based samples." (PMID 39315086, 2024). "We hypothesized that mesothelin could be used as a reliable diagnostic biomarker for canine mesotheliomas since it has been used as a cancer biomarker for human mesothelioma." (PMID 39315086, 2024). "We hypothesized that mesothelin could act as a reliable diagnostic marker for canine mesotheliomas based on the biological similarities between human and canine mesotheliomas." (PMID 39315086, 2024). "In addition, the mesothelial marker, Wilms’ tumour 1 (WT1), is commonly coexpressed with MSLN and immunoreactivity is similarly associated with improved survival in mesothelioma." (PMID 37040900, 2023). "Another mesothelial marker, podoplanin (D2‐40), is commonly co‐expressed with MSLN in mesothelioma, has an association with improved prognosis and may have an inverse relationship with atypia." (PMID 37040900, 2023). "Each of these associations could explain the prognostic significance of MSLN expression in mesothelioma." (PMID 37040900, 2023). "Indeed, the most attractive antigen target in mesothelioma tumors is represented by mesothelin because of its overexpression and clear association with tumor aggressiveness." (PMID 35785199, 2022). "In the current study, we compared the diagnostic ability of mesothelin and midkine to differentiate mesothelioma from other pleural disease, and we firstly demonstrated to our knowledge that serum midkine levels possessed a prognostic value in mesothelioma." (PMID 28335760, 2017). "The new protein, which contains a large deletion of domain II and 10 amino acid mutations in domain III, is very cytotoxic to mesothelioma cells as well as other cancer cell lines, is well tolerated by mice and produces complete remissions of mesothelin expressing cancers in mice." (PMID 27167198, 2016). "Mesothelin (MSLN) is a 40-kDa glycosylphosphatidylinositol-linked cell surface antigen present in normal mesothelial cells and overexpressed in several human malignancies, including mesothelioma, pancreatobiliriary, ovarian and lung adenocarcinomas." (PMID 25506917, 2014). "As for secreted N-ERC/mesothelin, we previously devised a novel enzyme-linked immunosorbent assay (ELISA) system for determining its concentration in serum and showed that it is useful for diagnosing human mesothelioma." (PMID 24146039, 2014). "While pleural fluid and serum mesothelin are diagnostic biomarkers for mesothelioma, a similar biomarker for non-mesothelioma MPEs may have considerable clinical utility." (PMID 23009708, 2012).
mesothelioma (continued). "C-ERC/mesothelin is highly expressed in mesotheliomas and is a potential target for radioimmunotherapy (RIT)." (PMID 41901346, 2026). "Results: mAb 22A31 showed specific binding considering the level of C-ERC/mesothelin expression in each mesothelioma cell line." (PMID 41901346, 2026). "This study included eight patients with MSLN-positive advanced ovarian cancer or mesothelioma who had failed second-line or later treatments." (PMID 41400642, 2025). "In another clinical study, patients with mesothelioma, pancreatic cancer, or other mesothelin-positive solid tumors received amatuximab monotherapy for four weeks." (PMID 41400642, 2025). "Antibody–drug conjugates targeting mesothelin, a cell surface glycoprotein commonly overexpressed by mesothelioma, have also been evaluated." (PMID 40266436, 2025). "Over the years, high levels of MSLN expression have been reported in tissues and peripheral blood across a wide range of malignancies, including mesothelioma, ovarian, pancreatic, and esophageal cancers." (PMID 41335396, 2025). "Mesothelin is another molecule that has recently been frequently targeted in various forms of solid, epithelial cancers, including mesothelioma." (PMID 40002287, 2025). "Fn3 5.3.2 has shown rapid internalization, high specificity and affinity for MSLN-positive mesothelioma cells, as well as capability of bioconjugations to radiometal chelators, paving the way for the development of MSLN-targeting radio-Fn3 moieties." (PMID 41335396, 2025). "Taken together, these studies suggest that MSLN has a key role in cancer growth and metastasis beyond mesothelioma." (PMID 40240561, 2025). "This promising therapeutic candidate was evaluated in a phase I clinical trial including 59 patients with MSLN-positive advanced solid tumors, with mesothelioma and OC patients included in the dose expansion phase (NCT02955251)." (PMID 41335396, 2025). "Emerging molecular targets in mesothelioma include mesothelin (MSLN), oxytocin receptor (OXTR), protein arginine methyltransferase (PRMT5), and carbohydrate sulfotransferase 4 (CHST4)." (PMID 40362535, 2025). "This fusion protein has been proven to exert antitumor effects mediated by tumor-specific CD8+ T cells in mouse models of mesothelin-expressing cancers, including mesothelioma." (PMID 40918456, 2025). "Overexpression of mesothelin enhances cellular adhesion, facilitating local tumor invasion and the development of mesothelioma." (PMID 41375064, 2025). "The doxorubicin-loaded, mesothelin-targeted APMS (APMS-MB-DOX) were then administered via intraperitoneal (i.p.)injection in SCID mice carrying xenografts of human HMESO mesothelioma cells." (PMID 40918456, 2025). "Its low expression in normal mesothelial cells makes MSLN a promising candidate for targeted immunotherapy in mesothelioma patients." (PMID 41226368, 2025). "The targeted antigen for our A101 CAR-T cells is mouse mesothelin (Msln) which is an antigen expressed in solid tumors such as mesotheliomas, pancreatic, ovarian, and lung carcinomas." (PMID 40568084, 2025). "Mesothelin is a glycoprotein, and its role as a biomarker in mesothelioma has been reviewed elsewhere." (PMID 40002287, 2025). "MSLN, mesothelin, is a protein involved in cell adhesion function in normal cells but overexpressed in various cancer cells, including mesothelioma and lung, pancreas and CRC." (PMID 40565299, 2025). "Mesothelin (MSLN) is a tumor-associated glycoprotein overexpressed in NSCLC and mesothelioma, associated with poor prognosis and resistance to chemotherapy, and has limited expression in normal tissues, making it an attractive CAR T-cell target." (PMID 40940995, 2025). "We quantified expressed canine mesothelin transcripts via reverse transcription polymerase chain reaction (RT-PCR) and sequenced them using ribonucleic acid (RNA) extracted from a canine mesothelioma cell line." (PMID 39315086, 2024).